PSEN1 (presenilin 1)
Diseases named in the same sentence as PSEN1 in open-access papers (continued):
Sharing a sentence is not in itself a finding about the gene and the disease.
Alzheimer disease (continued). "After 6 h, Rg3 (50 μM) has been found to reduce Aβ levels in cultured primary neurons and in the brains of mice models of Alzheimer’s disease by decreasing the association of presenilin-1 (PS1) with lipid rafts and inhibiting Υ-secretase activity." (PMID 33041822, 2020). "PSEN1 has already been implicated in Alzheimer's disease as well as other neurodegenerative and neuropsychiatric disorders." (PMID 32735660, 2020). "We report a probable pathogenic Thr119Ile mutation in presenilin-1 (PSEN1) in two unrelated Korean patients, diagnosed with early onset Alzheimer’s disease (EOAD)." (PMID 32545847, 2020). "PSEN1 Glu184Gly was previously reported in French families with frontal variant Alzheimer’s disease (AD)." (PMID 32121568, 2020). "Pathogenic variants in the PSEN1 gene are known to be the most common cause of early-onset Alzheimer’s disease but there are few data on the frequency and spectrum of PSEN1 variants in Korea." (PMID 32103039, 2020). "A previous study in early-onset Alzheimer’s disease reported that 14% of mutations of the presenilin 1 (PSEN1) gene in brain cells are responsible for the initiation of this disease." (PMID 32549191, 2020). "A pathogenic mutation in PSEN1 p.Glu184Gly was discovered in a Thai family with early onset Alzheimer’s disease (EOAD) as the first case in Asia." (PMID 32121568, 2020). "Well over 200 mutations causing familial Alzheimer’s disease have been identified in the human PSEN1 and PSEN2 genes." (PMID 32658922, 2020). "PS1 has been most studied in the context of Alzheimer’s disease (AD), largely because mutations that cause early onset of AD are found most frequently in Psen1 gene and PS1 also plays a key role in Aβ production." (PMID 32822378, 2020). "We report the generation of an allelic, isogenic series for the familial Alzheimer’s disease mutation PSEN1 intron 4 deletion as well as total presenilin-1 knockout." (PMID 32395715, 2019). "Stx5 interacts directly with presenilin 1 and 2 via both its Habc regulatory domain and transmembrane helix, and these interactions are reduced in a mutant of presenilin 1 that is associated with Alzheimer’s disease." (PMID 31357511, 2019). "In this community, Alzheimer’s disease is quite common as a result of the high frequency of the autosomal dominant and fully penetrant PSEN1 E280A allele." (PMID 30112632, 2019). "Familial Alzheimer’s disease (FAD)-associated presenilin 1 (PS1) serves as a catalytic subunit of γ-secretase complex, which mediates the proteolytic liberation of β-amyloid (Aβ) from β-amyloid precursor protein (APP)." (PMID 30682043, 2019). "Impairment of γ-secretase carboxypeptidase activity, such as is caused by some familial Alzheimer’s disease mutations in APP or PSEN1 or PSEN2, can result in similar changes to the amyloid-β isoform ratios." (PMID 29945247, 2018). "Rare early-onset familial forms of Alzheimer’s disease (AD) are associated with autosomal dominant mutations in the amyloid beta precursor protein (AβPP), presenilin 1 and presenilin 2 genes." (PMID 29520228, 2018). "The subjects are carriers of the PSEN1 mutation, which leads to early onset Alzheimer’s disease, but at the time of EEG acquisition in 1999, these subjects were cognitively unimpaired." (PMID 29562504, 2018). "PSEN1 p.P284L and PSEN1 c.857-1G>A mutations are reported to relate to Alzheimer’s disease with spastic paresis, which is pathologically characterized by large, noncored, weakly neuritic Aβ-amyloid plaques called “cotton-wool” amyloid plaques (CWP)." (PMID 30090657, 2018). "STIM2 knockdown was reported to rescue the amplitude of SOCE and attenuate intracellular Ca2+ load in a cellular model of Alzheimer’s disease that was caused by the expression of mutant presenilin 1 M146V." (PMID 30455632, 2018). "Hung and Livesey demonstrate that mutations in APP and PSEN1 that are causal for early onset Alzheimer’s disease lead to major defects in lysosome function and autophagy in human neurons." (PMID 30590039, 2018).
Alzheimer disease (continued). "The situation is the same for the variant p.L173F found in PSEN1, it was described as pathogenic in families with Alzheimer’s disease and parkinsonism." (PMID 29867446, 2018). "Familial Alzheimer’s disease (AD) is predominantly caused by presenilin 1 (PSEN1) or presenilin 2 (PSEN2) mutations." (PMID 29875678, 2018). "In a cohort including patients with familial Alzheimer disease as well as sporadic cases of early-onset Alzheimer disease, Dominique Campion and colleagues identify previously unreported mutations to PSEN1 and PSEN2." (PMID 28350801, 2017). "Alzheimer’s disease (AD)-linked protein, presenilin 1 (PS1), is present at the synapse, and the knock-out of presenilin in mice leads to synaptic dysfunction." (PMID 28193235, 2017). "The Presenilin 1 gene (PSEN1) is one of the genes known to affect Alzheimer’s disease risk; it codes for a transmembrane protein that forms the core of the gamma secretase complex, an enzyme that cleaves amyloid precursor protein into β-amyloid peptides." (PMID 27357204, 2016). "Multiple studies have identified novel variants in the PSEN1 gene that affect Alzheimer’s disease status." (PMID 27357204, 2016). "A number of mutations in APP and PSEN1 genes were identified as a cause of hereditary form of Alzheimer disease." (PMID 26851889, 2016). "Multiple studies have attempted to locate novel variants in the PSEN1 gene that affect Alzheimer's disease status." (PMID 27357204, 2016). "This enzyme consists of multiple subunits, and a mutation in one of these – presenilin-1 – causes a particularly severe form of Alzheimer’s disease." (PMID 27196744, 2016). "A recent study suggested that one of these variants, PSEN1 E318G (rs17125721), significantly affects Alzheimer's disease status in a large case–control dataset, particularly in connection with the APOEε4 allele." (PMID 27357204, 2016). "We previously reported age of onset (AOO) modifier genes in the world's largest pedigree segregating early-onset Alzheimer's disease (AD), caused by the p.Glu280Ala (E280A) mutation in the PSEN1 gene." (PMID 26949549, 2016). "Presenilin 1 (PSEN1) gene is one of four important genes that are linked to inherited forms of the Alzheimer's disease (AD)." (PMID 27034902, 2016). "Both NPTXR and VGF were found to be significantly different in a CSF of presymptomatic persons with familiar Alzheimer’s disease due to PSEN1 and APP mutations as compared to related non carriers by high resolution LC-MS." (PMID 26270474, 2015). "For example, the latest evidence indicates that PSEN1, p.E318G variant is associated with the development of early-onset of Alzheimer’s disease (AD) for APOE-ε4 carriers." (PMID 26047637, 2015). "Studies from literature have suggested that mis-regulation of canonical WNT signaling can be involved in Alzheimer’s disease (AD) due to the fact that AD patients that carries a mutation in presenilin-1 have very low levels of β-Catenin." (PMID 26647069, 2015). "HLA class I mediated signaling has been studied, and it was observed that specifically HLA-A2 is substrate for the Alzheimer's disease-associated presenilin-1/gamma-secretase." (PMID 25197660, 2014). "Mutations of presenilin 1 or amyloid precursor protein cause familial susceptibility to Alzheimer's disease." (PMID 23825632, 2013). "The discovery of monogenic forms of Alzheimer's Disease (AD) associated with mutations within PSEN1, PSEN2, and APP genes is giving a big contribution in the understanding of the underpinning mechanisms of this complex disorder." (PMID 24377094, 2013). "Mutations in the presenilin 1 gene, affecting the function of γ-secretase, are the most common genetic cause of familial, early-onset Alzheimer's disease." (PMID 23593396, 2013). "Missense mutations in three different genes encoding amyloid-β precursor protein, presenilin 1 and presenilin 2 are recognized to cause familial early-onset Alzheimer disease." (PMID 22044463, 2011).
Alzheimer disease (continued). "While mutations in presenilin 1, presenilin 2 and β-amyloid precursor protein gene are highly penetrant causes of early-onset Alzheimer’s disease, these together account for less than 1 per cent of cases of Alzheimer’s disease in the general population." (PMID 21150010, 2010). "Studies of autophagic pathology in Alzheimer's disease indicate that presenilin-1 mutations promote Aβ peptide production by impairing lysosomal function and thereby preventing autolysosome degradation of accumulating Aβ peptides." (PMID 19640278, 2009). "For example, mutations in the presenilin 1 and 2 genes have been linked to early onset familial forms of Alzheimer's disease (FAD)." (PMID 19730737, 2009). "Familial Alzheimer's disease-linked variants of presenilin (PSEN1 and PSEN2) contribute to the pathophysiology of disease by both gain-of-function and loss-of-function mechanisms." (PMID 18834536, 2008). "The specific extent of genotype alteration that links PSEN1 mutations to seizures in Alzheimer’s disease (AD) remains unclear." (PMID 40149496, 2025). "Our results indicate a pre-existing Alzheimer’s disease-like pathology caused by the presenilin 1 mutation, with increased beta-amyloid aggregates in both the cell lysate and conditioned media compared to isogenic controls and also increased intracellular tau aggregates." (PMID 39749010, 2025). "Studies have implicated PSEN1 dysfunction in both Alzheimer’s disease and cancer." (PMID 40137900, 2025). "PSEN1 R269H is a known pathogenic variant causing early-onset Alzheimer’s disease (EOAD)." (PMID 39606324, 2024). "By employing source-reconstructed MEG in cognitively unimpaired individuals carrying mutations in the APP and PSEN1 genes, this study aimed to provide increased insights on quantitative neurophysiological alterations during a true early stage of Alzheimer’s disease." (PMID 39713236, 2024). "PSEN1 is linked to frontotemporal dementia and Alzheimer’s disease." (PMID 38037155, 2023). "Furthermore, impeded V-ATPase assembly and function due to impaired subunit a1 glycosylation and stability upon mutations to presenilin-1 (PS-1) was observed in the Alzheimer’s disease (AD) mouse model." (PMID 37465367, 2023). "Presenilin-1 mutation Alzheimer’s disease: A genetic epilepsy syndrome?" (PMID 35936776, 2022). "A typical example is given by the presenilin 1 mutation which has protected over the centuries against very high perinatal mortality (the carriers of the mutation survived) but then develops hereditary Alzheimer’s disease at about the age of 40 years old." (PMID 36140389, 2022). "In this situation, consideration should be given to proteins identified in lymphocytes that are associated with neurodegeneration like Alzheimer’s’ disease, including in particular proteins encoded by the amyloid protein precursor and the presenilin 1 and 2 genes connected with Alzheimer’s disease." (PMID 34067945, 2021). "Likewise, Alzheimer’s disease-associated familial mutations in presenilin 1 protein caused defective neurogenesis." (PMID 34572052, 2021). "Finally, dysregulation of Alzheimer's disease-associated genes including amyloid protein precursor, α-secretase, β-secretase, presenilin 1, presenilin 2, and tau protein occurs in a course of postischemic neurodegeneration." (PMID 34527172, 2021). "It provides Alzheimer's disease-linked gene changes of the amyloid protein precursor, α-secretase, β-secretase, presenilin 1, presenilin 2, and tau protein in experimental post-ischemic injury in the CA1 and CA3 areas of the hippocampus and medial temporal cortex." (PMID 33679381, 2021). "In addition, human induced pluripotent stem cell (iPSC) neurons carrying an Alzheimer's disease-causing mutation in presenilin-1 undergo tau seeding more rapidly than control iPSC neurons." (PMID 33893219, 2021).
Alzheimer disease (continued). "Here we show, we believe for the first time, that circulating lymphocytes in post-asphyxia neonates overexpress the presenilin 1 and 2 genes with age, which genes are associated with neurodegenerative diseases i.e., post-ischemic brain injury and Alzheimer’s disease." (PMID 34067945, 2021). "In addition, three gene mutations are responsible for Alzheimer’s disease, including presenilin 1 (PSEN1), presenilin 2 (PSEN2) and amyloid precursor protein (APP), with presenilin 1 being the most common." (PMID 32085610, 2020). "In this regard, we co-transfected hPSCs with pEF-XMAS1xStop/2xStop and pEF-ABEmax along with a pDT-sgRNA targeting genomic Site-1 or single base pair changes in AKAP9 and PSEN1 that have been previously associated with increased risks of developing Alzheimer’s disease (AD)." (PMID 33317513, 2020). "Although approximately 90% of Alzheimer’s disease cases occur sporadically, mutated genes coding for either amyloid precursor protein (chromosome 21) or presenilin-1 (PS1; chromosome 14) or presenilin-2 (PS2; chromosome 1) are found in early-onset familial forms of AD." (PMID 32079163, 2020). "Presenilin-1 (PSEN1) is one of the causative genes for early onset Alzheimer’s disease (EOAD)." (PMID 31391004, 2019). "Interestingly, similar substitutions located in the highly conserved transmembrane domains of presenilin, encoded by the gene PSEN1, have been reported in patients with Alzheimer's disease." (PMID 31448880, 2019). "Although mutations in amyloid precursor protein (APP) and its proteases presenilin-1 and 2 have a causative relationship with the onset of familiar form of Alzheimer’s disease (FAD), overt manifestation of clinical AD is often preceded by a prolonged incubation period." (PMID 31453805, 2019). "Autosomal dominant (familial) Alzheimer's disease, due to mutations in presenilin 1 (PSEN1), presenilin 2 (PSEN2), or amyloid precursor protein (APP) genes, shares many features, both pathophysiologically and clinically, with the much more common sporadic form of the disease." (PMID 29413314, 2018). "Additionally, defects in PSEN1 expression are associated with the manifestation of Alzheimer’s disease in old age." (PMID 28732515, 2017). "Proteins often consist of several peptide domains, each of which is often encoded by a single exon within the gene, and sequence deletion can be associated with some human diseases; deletion of exon 9 of the presenilin 1 gene (PSEN1) causes some forms of Alzheimer's disease." (PMID 26414877, 2016). "Moreover, Comet assay revealed the apoptotic DNA fragmentation, while PCR-SSCP pattern and direct sequencing showed point mutation of Presenilin 1 gene at exon 5, gene linked to inherited forms of the Alzheimer's disease." (PMID 27034902, 2016). "To gain an insight into molecular events underlying neuronal activity-regulated Aβ production at the synapse, we explored functional outcomes of the newly discovered calcium-dependent interaction between Alzheimer’s disease-associated presenilin 1 (PS1)/γ-secretase and synaptic vesicle proteins." (PMID 27036734, 2016). "Indeed, many mouse models of Alzheimer's disease (AD), such as Presenilin-1 with both M146V and ΔExon9 mutations in knock-in mice and transgenic mice with the Swedish APP mutation, showed decreased adult neurogenesis." (PMID 25941474, 2015). "In the A375 cell line, the down-regulation of CEPBA could be responsible of the up-regulation of PSEN1 (presenilin 1), mutated in patient with sporadic early-onset Alzheimer's disease." (PMID 25077705, 2014). "SNP rs6894869 was significantly associated with lipid particle size phenotype BMED and mapped to an intron of CTNND2, which functions in the same pathway as cadherins, plays a crucial role in CNS development and is a partner of the Alzheimer disease-associated gene presenilin-1." (PMID 23628382, 2013). "This deleterious dual effect might explain why FAD-linked PSEN1 mutations cause early onset Alzheimer's disease." (PMID 22529981, 2012).
Alzheimer disease (continued). "Alzheimer’s disease is perhaps the most widespread neurodegenerative disorder of the elderly, with most familiar cases attributed to several mutations in presenilin 1 and 2, genes whose protein products are responsible for the proteolytic cleavage of the amyloid precursor peptide (APP)." (PMID 23060904, 2012). "This may be exemplified by the finding that some mutations in the PSEN1 gene lead to an onset of symptoms of Alzheimer’s disease patients in their twenties or thirties." (PMID 22654716, 2011). "Primary neurons from GD3S−/− mice are resistant to neurotoxicity induced by amyloid-β or hyperhomocysteinemia, and when GD3S is eliminated in the APP/PSEN1 double-transgenic model of Alzheimer's disease the plaque-associated oxidative stress and inflammatory response are absent." (PMID 22195039, 2011). "Reports of somatic point mutations in presenilin 1 gene in a case of sporadic early onset Alzheimer's disease and in the PRNP gene in a sCJD case suggest that somatic point mutations in other coding positions in PRNP may also lead to sCJD." (PMID 22028931, 2011). "The evidence that mutations in PSEN1/PSEN2 that cause Familial Alzheimer's disease are loss of function mutants, and that loss of PSEN1/PSEN2 function causes neurodegeneration in mice, supports this hypothesis." (PMID 20661273, 2010). "Finally, the familial form of Alzheimer's disease (AD), in which the presenilin-1 (PSEN1) gene is mutated, has been correlated with reduced levels of active β-catenin." (PMID 20150991, 2010). "Notably, previous in vitro studies provided evidence that DNA methylation is involved in transcriptional regulation of PSEN1 an Alzheimer's disease-associated gene and regulator of amyloid precursor protein and Notch signaling pathways." (PMID 17878930, 2007). "In addition to Alzheimer's disease, several recent studies have linked PSEN1 to familiar frontotemporal dementia." (PMID 16930451, 2006). "Furthermore, presenilins, which are part of the molecular machinery that processes APP, when mutated are responsible for most of the cases of familial AD; more than 70 different mutations in presenilin 1 (PS1) have been associated with inherited early onset Alzheimer’s disease." (PMID 37240836, 2023). "Presenilin 1 (PSEN1) is an important component of γ-secretase, and its mutations would lead to apoptosis, neurodegeneration, and cognitive decline, which might cause the occurrence and progression of Alzheimer’s disease." (PMID 34568005, 2021). "In Alzheimer's disease cell death may be caused by compromised endogenous neuroprotection due to impaired synaptic transmission and synapse loss caused by A-β or changes in calcium homeostasis or calcium signaling in neurons expressing mutant presenilin-1." (PMID 19680447, 2009). "Alzheimer’s disease is strongly linked to rare mutations in APP, PSEN1, and PSEN2 genes, while the APOE allele represents the strongest genetic risk factor for sporadic AD." (PMID 41143248, 2025). "Mutations that lead to the development of early-onset Alzheimer’s disease are found within the APP (amyloid precursor protein), PSEN1 (presenilin 1), and PSEN2 (presenilin 2) genes, the products of which regulate the production of Aβ." (PMID 40869138, 2025). "Knockdown of circRNA_0004381 reduced hippocampal neuronal injury and promoted microglia M2-type polarization by the miR-647/PSEN1 axis, ultimately improving cognitive function in a mouse model of Alzheimer’s disease." (PMID 41245147, 2025). "Aberrant DNA methylation has been observed in genes linked to neurodegeneration, including APP, PSEN1, and TREM2 in Alzheimer’s disease (AD), as well as SNCA and LRRK2 in Parkinson’s disease (PD)." (PMID 40076852, 2025). "While most Alzheimer’s disease cases are sporadic, FAD mutations in PSEN1, PSEN2, and APP are nearly completely penetrant." (PMID 39754192, 2025).